TNF (tumor necrosis factor)
Diseases named in the same sentence as TNF in open-access papers (continued):
Sharing a sentence is not in itself a finding about the gene and the disease.
pneumonic plague (3 papers, 2009 to 2013). A plague in which the bacteria have infected the lungs. "Indeed, it was previously shown that injection of IFNγ and TNFα protects mice against Y. pestis infection and that neutralization of these cytokines abrogates vaccine-induced protection against pneumonic plague." (PMID 22348169, 2012). "Both IFN-γ and TNF-α are important for innate immunity, as well as to elicit TH1 immune responses that might be essential for protection against pneumonic plague." (PMID 23853602, 2013). "Protection against bubonic plague is primarily antibody-mediated, while protection against pneumonic plague may require cell mediated immunity induced by INF-γ and TNF-α." (PMID 19701461, 2009).
podoconiosis (3 papers, 2024). A disease of the lymphatic vessels of the lower extremities that is caused by chronic exposure to irritant soils. "Consistent with this possibility, we observed higher levels of TNF-α and IL-1β in unstimulated culture wells and IL-1β mRNA in the peripheral blood of podoconiosis patients (manuscript in preparation)." (PMID 38448477, 2024). "The cytokine profile for podoconiosis patients by stage severity suggests trends of reduced IL-10 levels as the disease becomes more severe, while TNF-α appears to increase with severity." (PMID 39689160, 2024). "Even though podoconiosis patients compared to controls showed a reduction in TNF-α levels, when looking at the data by disease stage, the TNF-α levels increase in relation to the severity." (PMID 39689160, 2024). "These two innate cells are the predominant sources of pro-inflammatory cytokines, and the higher levels of TNF-α and IL-1β in podoconiosis patients may have resulted from these activated phagocytic cells." (PMID 39591258, 2024). "Our result from the overnight stimulation experiment showed that TNF-α levels were elevated in the supernatants from podoconiosis patients in unstimulated cultures compared to healthy controls, with a median value of 783.6 pg/mL vs. 445 pg/mL, respectively (p = 0.04)." (PMID 39591258, 2024). "Hence, this suggests that the two cytokines (TNF-α and IL-1β) may work synergistically in driving the inflammatory process in podoconiosis patients." (PMID 39591258, 2024).
premature ovarian failure (3 papers, 2015 to 2025). "In fact, lower levels of TNF-alpha are associated with premature ovarian failure, which may seem contradictory." (PMID 40713717, 2025). "hAEC transplantation promotes ovarian function by inhibiting tumor necrosis factor-alpha-mediated cell apoptosis and reducing inflammation in chemotherapy-induced premature ovarian failure." (PMID 26303743, 2015).
progeria (3 papers, 2018 to 2021). "Accordingly, elevated expression of TNF-α and IL-6 by the over-activation of NF-κB has been proven to occur in both physiological aging and in progeria human diseases." (PMID 30631004, 2019). "Moreover, WS-ECs, but not HGPS-ECs, exhibited a more pronounced response to inflammatory factor TNF-α, again indicating different molecular pathologies between the two progeroid syndromes." (PMID 29476423, 2018).
Proteinopathies (3 papers, 2022 to 2025). "In addition to the emergence of compound proteinopathies in wide brain regions, we performed IHC with antibodies specific for Iba1, GFAP and TNFα to assess the extent of gliosis and neuroinflammation, which are key features in neurodegenerative diseases." (PMID 40307569, 2025).
Pseudomonas infection (3 papers, 2016 to 2022). Infections with bacteria of the genus pseudomonas. "Acute Pseudomonas infection drives inflammatory cytokines such as TNF and IL-1β." (PMID 34237078, 2021). "The levels of plasma IL-6, TNF-α, IFN-γ and MIP-2 were significantly higher in infected mice and in the IL-15 SA-treated mice receiving intraperitoneal Pseudomonas infection as compared to vehicle treated infected mice." (PMID 26859674, 2016). "For Pseudomonas infection settings, sham-treated mice expressed detectable TNF, but not IL-1β, in lungs." (PMID 34237078, 2021).
pulmonary fungal infections (3 papers, 2009 to 2016). "The type 1 cytokines IFN-γ, TNFα and GM-CSF played critical and overlapping roles in the clearance of pulmonary fungal infection." (PMID 22829762, 2012). "IFN-γ and TNF-α have been shown to be important mediators of protection against other pulmonary fungal infections." (PMID 19727388, 2009). "Consistently, our data demonstrated that early TNF-α signaling is required for robust DC accumulation in the LALN, especially the CD11b+ DC subset, which has been shown to be particularly important for priming protective Th17 cell responses to pulmonary fungal infections." (PMID 27406560, 2016).
purpura (3 papers, 2014 to 2023). A small blood vessel hemorrhage into the skin and/or mucous membranes. "Indeed, palpable purpura is the most frequent clinical manifestation of LCV associated with anti-TNF therapy." (PMID 37176606, 2023).
radiculitis (3 papers, 2018 to 2025). An inflammatory process affecting a nerve root. "One study evaluated the intrathecal administration of low-dose ozone (10–30 μg/mL) in a model of chronic radiculitis, which led to a significant reduction in proinflammatory cytokines, such as TNF-α, IL-6, and IL-1β, and improved mechanical allodynia." (PMID 39598204, 2024). "We speculate that intrathecal administration of low-concentration O3 diminishes radicular inflammation by reducing TNF-α, IL-1β, and IL-6 in radiculitis rats." (PMID 30651902, 2018). "Intrathecal administration of 10 μg/mL, 20 μg/mL, or 30 μg/mL oxygen/ozone significantly attenuated the decreased mechanical PWTs, downregulated the overexpression of spinal TNF-α, IL-1β, and IL-6, and increased the expression of cGMP and cAMP in chronic radiculitis rats." (PMID 30651902, 2018).
Respiratory distress (3 papers, 2022 to 2025). Respiratory distress is objectively observable as the physical or emotional consequences from the experience of dyspnea. "Furthermore, higher plasma levels of IL-6, IL-1β, IL-8, CCL2, (among other markers such as TNF-α) and IL-6 were also associated with post-TBI mortality, whereas higher levels of IL-6 and IL-8 were associated with respiratory distress in TBI patients." (PMID 37415924, 2023).
Rickettsia infection (3 papers, 2022 to 2025). "Transcriptome analysis revealed significant enrichment of the TNF-signaling pathway and genes associated with both necroptosis and apoptosis, suggesting their potential involvement during Rickettsia infection." (PMID 40607949, 2025). "Transcriptomic analysis further reveals that Rickettsia infection upregulates the host tumor necrosis factor (TNF) and NF-κB signaling pathways, which subsequently suppress RIPK1 kinase activity and contribute to the inhibition of host cell death." (PMID 40607949, 2025). "Increased inflammatory responses characterized by Interferon (IFN)-α, Tumor Necrosis factor (TNF)-α, and Interleukin(IL)-1 increased serum levels have been reported in both human mild and severe Rickettsia infections." (PMID 36551320, 2022). "Rickettsia infection usually leads to an increased vascular permeability and release of tumor necrosis factor alpha (TNF-alpha)." (PMID 36136825, 2022).
ROSAH syndrome (3 papers, 2022 to 2025). "ADP-heptose-dependent IL-8, CCL3 and TNF secretions were increased in the supernatant of monocytes from ROSAH syndrome patients in the presence of IFN-γ." (PMID 39868044, 2025). "We also found that untreated patients with ROSAH syndrome had frequent elevations of CRP and proinflammatory plasma cytokines including TNF and IL-6." (PMID 35868845, 2022).
S. strongyloides infection (3 papers, 2021 to 2025). "A diminution in mycobacterial-specific Th1 cells and Th17 cells and their relevant cytokines (i.e., IFN-γ, TNF-α and IL-2, IL-17A, and IL-17F) has been found in patients with concomitant filarial or Strongyloides infection." (PMID 34202662, 2021). "TNF-α may play a role in the control of S. strongyloides infection based on the observation that TNF-α blockers have been reported to induce hyperinfection in patients infected with S. stercoralis." (PMID 34314415, 2021).
Schistosoma haematobium infection (3 papers, 2010 to 2023). "The study explored the association between single nucleotide polymorphisms (SNPs) in interleukin-10 (IL-10) and tumour necrosis factor alpha (TNF-α) promoter regions and susceptibility to Schistosoma haematobium infection." (PMID 34485462, 2020). "Schistosoma haematobium infection status had significant greater odds of low performance in the Foundations of Learning Domain in PSAC who were categorized as having high TNF-α." (PMID 37143686, 2023).
senile cataract (3 papers, 2016 to 2023). A cataract with no obvious cause occurring in persons over 50 years old. "In addition, one population-based study showed that several systemic inflammatory mediators (high sensitivity C-reactive protein, tumor necrosis factor α, interleukin-6, and intracellular adhesion molecule-1), were associated with age-related cataracts." (PMID 27861567, 2016). "We found that the concentrations of IL-8, MMP-2, MMP-3, MMP-9, TGFβ-1, TGFβ-2, TGFβ-3, SAA, and TNF-α were significantly elevated in JIAU samples compared with the control group (senile cataract patients)." (PMID 29675026, 2018).
sensorineural hearing loss (3 papers, 2016 to 2023). "In humans, elevated TNF‐α serum levels have been detected in people with idiopathic sudden sensorineural hearing loss and immune‐medicated sensorineural hearing loss." (PMID 26791792, 2016). "Elevated levels of serum TNF‐α are associated with human sensorineural hearing loss via poorly understood mechanisms." (PMID 26791792, 2016). "Whether the elevated level of TNF-α is the cause of or the consequence of sensorineural hearing loss, TNF-α blockade is expected as an avenue for treatment of immune-mediated hearing loss." (PMID 37733709, 2023).
Sheehan syndrome (3 papers, 2014 to 2025). "The results of the present study indicate that patients with Sheehan syndrome haveelevated levels of the inflammatory markers IL-6 and TNF-α compared withhealthy controls." (PMID 40741991, 2025). "Patients with Sheehan syndrome, compared with healthy controls, had significantlyhigher mean TNF-α levels (23.41 ± 10.97 pg/mLversus 20.05 ± 2.76 pg/mL; p = 0.041) and mean IL-6levels (37.19 ± 5.38 pg/mL versus 32.08 ± 1.18pg/mL; p = 0.004)." (PMID 40741991, 2025).
skin changes (3 papers, 2017). "Also, the levels of TNF-α and IL-6 in patients with cyanosis are higher than those in acyanotic individuals." (PMID 28469687, 2017).
squamous cell carcinoma of the oropharynx (3 papers, 2013 to 2021). "Some scholars consider that TNF-α SNPs (rs1800629, rs1799724, rs1800630, and rs1799964) may individually or, more likely, jointly affect individual susceptibility to HPV16-associated OSCC, particularly squamous cell carcinoma of the oropharynx (SCCOP) in never smokers." (PMID 34150619, 2021).
Strabismus (3 papers, 2017 to 2021). A misalignment of the eyes so that the visual axes deviate from bifoveal fixation. "We found the expression of INF-γ, IL-10, IL-12p70, and IL-17A in tears of strabismus patients, which were no significantly higher than those of normal subjects, while IL-6 and TNF-α were statistically significant." (PMID 34659636, 2021).
substance abuse (3 papers, 2020 to 2025). The use of a drug for a reason other than which it was intended or in a manner or in quantities other than directed. "Neuroinflammation, characterized by microglial activation and increased pro-inflammatory cytokines (such as IL-1β, IL-6, and TNF-α), is a potential mechanism behind the behavioral changes observed in individuals exposed to chronic stressors and substance abuse." (PMID 40563776, 2025).
systolic heart failure (3 papers, 2009 to 2020). Heart failure caused by abnormal myocardial contraction during systole leading to defective cardiac emptying. "In patients with systolic heart failure, IL-6 and TNF-α are associated with functional NYHA class." (PMID 19909503, 2009). "The positive effects of anti-TNF-α therapy in autoimmune inflammatory diseases encouraged testing its therapeutic value in patients with systolic heart failure." (PMID 33053859, 2020). "In conclusion, continuous anti-TNF-α therapy in patients with systolic heart failure show no evident benefits and may even be harmful and exacerbate the disease." (PMID 33053859, 2020).
Telangiectasia (3 papers, 2018 to 2025). Telangiectasias refer to small dilated blood vessels located near the surface of the skin or mucous membranes, measuring between 0.5 and 1 millimeter in diameter. "PAE, characterized by persistent telangiectasia and erythematous lesions, results from the sustained release of inflammatory cytokines such as interleukin‐6 and TNF‐α." (PMID 39601200, 2025).
Tension-type headache (3 papers, 2023 to 2025). A type of headache that last hours with continuous pain of mild or moderate intensity, bilateral location, a pressing/tightening (non-pulsating) quality and that is not aggravated by routine physical activity such as walking or climbing stairs. "Transforming growth factor (TGF)-β (SMD 0.52, 95% CI 0.18–0.86, p = 0.003) and TNF-α (SMD 0.64, 95% CI 0.33–0.96, p = 0.0001) were both higher in patients with tension-type headache than controls." (PMID 37016284, 2023). "There were significantly higher levels of both Transforming growth factor (TGF)-β (SMD 0.52, 95% CI 0.18–0.86, p = 0.003) and TNF-α (SMD 0.64, 95% CI 0.33, 0.96, p = 0.0001) in patients with tension-type headache." (PMID 37016284, 2023).
testicular dysfunction (3 papers, 2020 to 2026). "In testicular-inflammation, cytokines such as TNF-α, IL-1α and IL-1β are produced in significant levels, and are particularly known to aggravate testicular disease progression, and subsequent death." (PMID 33565293, 2021).
Testicular torsion (3 papers, 2014 to 2024). Testicular torsion is when the spermatic cord to a testicle twists, cutting off the blood supply. "Compared to the sham group, the levels of proinflammatory cytokines (IL-2 and TNF-α) and MDA were significantly increased in testes after testicular torsion, while the levels of SOD and GPx were decreased (resp., P < 0.05)." (PMID 24904198, 2014).
thrombotic microangiopathy (3 papers, 2023 to 2025). The syndromes of microangiopathic hemolytic anemia, thrombocytopenia, and variable signs of organ impairment, due to platelet aggregation in the microcirculation. "Circulating biomarkers of inflammation (C-reactive protein, ferritin, and 32 cytokines), immune depression (ex vivo tumor necrosis factor response to endotoxin < 200 pg/mL), thrombotic microangiopathy (ADAMTS13 activity <57%), and EBV seropositivity (viral capsid IgG) were measured." (PMID 40828536, 2025).
thyroid nodule (3 papers, 2023 to 2024). A small circumscribed mass in the THYROID GLAND that can be of neoplastic growth or non-neoplastic abnormality. "While tumor necrosis factor alpha is associated with some malignancies, studies on its effects on thyroid functions and thyroid nodules are limited." (PMID 39630724, 2024). "Patients using TNF-alpha inhibitors have a higher number of thyroid nodules and a higher frequency of nodules requiring FNAC according to EU-TIRADS criteria." (PMID 39630724, 2024). "This study aimed to assess the effect of tumor necrosis factor alpha inhibitors treatments on the evaluation of thyroid nodules and thyroid function tests in axial spondyloarthritis patients." (PMID 39630724, 2024). "This study aimed to evaluate the effect of TNF-alpha inhibitors on the evaluation of thyroid nodules and thyroid function tests in patients with axial spondyloarthritis." (PMID 39630724, 2024). "In a clinical study, 1800 patients with thyroid disease were divided into a thyroid nodule group and a non-nodule group, and serum levels of inflammatory factors such as IL-6 and TNF-α were measured, and regression analysis showed a positive correlation between thyroid nodules and IL-6 and TNF-α." (PMID 39494342, 2024). "Axial spondyloarthropathy patients using TNF-alpha inhibitors may have thyroid nodules more frequently than NSAID users." (PMID 39630724, 2024). "It should be considered that thyroid nodule evaluation may be necessary before starting TNF-alpha inhibitors and during treatment." (PMID 39630724, 2024). "Therefore, through transcriptomics in conjunction with literatures, we speculated that JJJG may treat thyroid nodules via (IL-6, TNF-α, IL-1β)/JAK2/STAT3/VEGF pathway." (PMID 39494342, 2024). "Meanwhile, this study is the first to explore and suggest that the (IL-6, TNF-α, IL-1β)/JAK2/STAT3/VEGF signaling pathway may be involved in regulating the development of thyroid nodules and is one of the possible therapeutic targets for JJJG." (PMID 39494342, 2024). "Transcriptomics suggested that the (IL-6, TNF-α, IL-1β)/JAK2/STAT3/VEGF pathway may be one of the key mechanisms in the treatment of thyroid nodules by JJJG." (PMID 39494342, 2024). "This study indicates that JJJG efficiently ameliorates thyroid nodules by regulating the levels of FT3, FT4 and TSH in serum and suppressing (IL-6, TNF-α, IL-1β)/JAK2/STAT3/VEGF pathway in thyroid tissue, providing a potential therapeutic approach for thyroid nodules." (PMID 39494342, 2024).
thyrotoxicosis (3 papers, 2009 to 2025). A hypermetabolic syndrome caused by the elevation of thyroid hormone levels in the serum. "Several previous reports have tried to address thecontribution of thyrotoxicosis to the rise in inflammatory cytokines such as IL-1,IL-6, IL-10, and TNF-alpha." (PMID 19343192, 2009). "It provides new insights into the roleof IL-10 and TNF-alpha in thyrotoxicosis." (PMID 19343192, 2009). "We hypothesized that reactive oxygen intermediates, that were induced by thyrotoxicosis, act as a signal for the release of cytokines like IL-6, IL-10, and TNF-alpha." (PMID 19343192, 2009).
Tourette syndrome (3 papers, 2021 to 2024). A neurologic disorder caused by defective metabolism of the neurotransmitters in the brain. "A recent meta-analysis found increased levels of proinflammatory cytokines in pediatric patients with Tourette syndrome, including TNF-α and IL-68." (PMID 38956051, 2024).
transverse myelitis (3 papers, 2024 to 2026). "Tumor necrosis factor-alpha (TNF-α) inhibitors have been infrequently associated with inflammatory central nervous system events, including transverse myelitis." (PMID 42187520, 2026).
Trichinella spiralis infection (3 papers, 2018 to 2025). "Trichinella spiralis infection markedly enhanced the levels of proinflammatory cytokines (TNF-α, IL-6, IL-17, and ICAM-1, P < 0.01) but remarkably reduced the level of anti-inflammatory cytokine (IL-10) in colon, compared with control group (P < 0.01)." (PMID 29662452, 2018). "Similar TNFα reductions, alongside other improvements, have been observed with albendazole and lactoferrin-loaded silver nanoparticles, as well as with eugenol, suggesting the latter’s potential as a trichinellosis treatment." (PMID 41026274, 2025). "This study suggests that S. officinalis possesses strong antifibrotic and anti-inflammatory properties, by downregulating FN1, TNF-α, and TGF-β while maintaining IL-10 expression, making it a valuable adjunct therapy for trichinellosis." (PMID 41026274, 2025).